EIF4EBP1 (eukaryotic translation initiation factor 4E binding protein 1)
Diseases named in the same sentence as EIF4EBP1 in open-access papers (continued):
Sharing a sentence is not in itself a finding about the gene and the disease.
malignant glioma (2 papers, 2015 to 2022). A grade III or grade IV glioma arising from the central nervous system. "Next, we asked whether EIF4EBP1 overexpression in malignant gliomas might be caused by EIF4EBP1 gene amplification." (PMID 35228525, 2022). "We then asked whether EIF4EBP1 mRNA expression is associated with common genetic and epigenetic alterations found in malignant gliomas." (PMID 35228525, 2022). "Based on these analyses, we can exclude EIF4EBP1 gene amplification or altered EIF4EBP1 promoter methylation as possible mechanisms driving EIF4EBP1 overexpression in malignant gliomas." (PMID 35228525, 2022). "Finally, by employing transient knock-down experiments to repress either of these transcription factors, we identified MYBL2 and ETS1 as the relevant transcriptional drivers of enhanced EIF4EBP1 expression in malignant glioma cells." (PMID 35228525, 2022). "We next reasoned that the increased EIF4EBP1 mRNA expression in malignant gliomas might be driven by specific transcription factors." (PMID 35228525, 2022). "Taken together, these data indicate that seven transcription factors could contribute to driving increased expression of EIF4EBP1 in malignant gliomas." (PMID 35228525, 2022). "Given that we found EIF4EBP1 to be a target gene of the ETS1 and MYBL2 oncoproteins in malignant gliomas, 4EBP1 may possibly contribute to ETS1 and MYBL2 tumorigenic functions in these tumors." (PMID 35228525, 2022). "Taken together, our findings confirm enhanced expression of EIF4EBP1 in malignant gliomas relative to non-neoplastic brain tissue and characterize the underlying molecular pathomechanisms." (PMID 35228525, 2022). "Thereby, we confirmed that malignant glioma tissues showed higher levels of EIF4EBP1 mRNA expression compared to non-neoplastic brain tissues in each of the analyzed cohorts." (PMID 35228525, 2022). "Analyzing the copy number status of EIF4EBP1 in 507 malignant glioma samples did not reveal any amplification of EIF4EBP1." (PMID 35228525, 2022). "We analyzed the DNA methylation level of 12 CpG sites within the EIF4EBP1 promoter region (hg19; Chr8: 37,886,520–37,889,020), which showed that non-neoplastic brain tissues and malignant glioma tissues exhibited a very similar methylation profile." (PMID 35228525, 2022). "Our analyses revealed that EIF4EBP1 overexpression in malignant gliomas is neither due to gene amplification nor to altered DNA methylation, but rather results from aberrant transcriptional activation by distinct transcription factors." (PMID 35228525, 2022). "We then assessed whether EIF4EBP1 mRNA overexpression is due to differential promoter methylation in non-neoplastic brain versus malignant glioma tissues." (PMID 35228525, 2022). "To identify potential transcription factor candidates, we searched for transcription factors that are positively co-expressed with EIF4EBP1 in malignant gliomas, overexpressed in these tumors as compared to non-neoplastic brain tissues, and known to bind the endogenous EIF4EBP1 promoter by ChIP." (PMID 35228525, 2022).
rheumatoid arthritis (2 papers, 2020 to 2024). A chronic, systemic autoimmune disorder characterized by inflammation in the synovial membranes and articular surfaces.
cryptorchidism (1 paper, 2025). The failure of one or both testes of a male fetus to descend from the abdomen into the scrotum during the late part of pregnancy. "The results highlight EIF4EBP1 as a potential therapeutic target for managing cryptorchidism-associated germ cell damage." (PMID 40486678, 2025). "By conducting both in vivo and in vitro experiments, we confirmed the association between EIF4EBP1 expression and increased germ cell apoptosis and autophagy in cryptorchidism." (PMID 40486678, 2025). "To further investigate the molecular pathology, we used bioinformatics analysis to identify EIF4EBP1, a gene differentially expressed in cryptorchidism and autophagy." (PMID 40486678, 2025). "Inhibition of E2F1 can effectively reduce apoptosis and excessive autophagy in germ cells of cryptorchidism by downregulating EIF4EBP1 expression, thereby alleviating testicular damage and the decline in fertility in cryptorchidism model mice." (PMID 40486678, 2025). "This study investigates the role of E2F1 in regulating EIF4EBP1 expression and its contribution to excessive autophagy and apoptosis in cryptorchidism." (PMID 40486678, 2025). "In summary, EIF4EBP1 significantly modulates apoptosis and autophagy in reproductive cells during cryptorchidism, and its increased expression likely contributes to the disease’s progression." (PMID 40486678, 2025). "In this study, we explored the pivotal role of EIF4EBP1 in the pathophysiology of cryptorchidism and examined the regulatory mechanism of its upstream regulator, E2F1." (PMID 40486678, 2025). "To explore the regulatory mechanisms of EIF4EBP1 in cryptorchidism, we investigated its upstream regulatory factors." (PMID 40486678, 2025). "Subsequent RT-qPCR and WB analyses revealed that EIF4EBP1 expression was significantly upregulated in the testicular tissues of cryptorchidism model mice." (PMID 40486678, 2025). "In summary, this study is the first to elucidate the critical role of EIF4EBP1 in the pathology of cryptorchidism and identify E2F1 as its upstream regulator." (PMID 40486678, 2025). "E2F1 is essential in the progression of cryptorchidism through its regulation of EIF4EBP1 expression." (PMID 40486678, 2025). "The results revealed that EIF4EBP1 was a key gene among the DEGs related to cryptorchidism and autophagy." (PMID 40486678, 2025). "E2F1 regulates EIF4EBP1 expression in cryptorchidism, contributing to excessive autophagy and apoptosis." (PMID 40486678, 2025). "RT-qPCR and WB analyses revealed a significant upregulation of EIF4EBP1 in both in vivo and in vitro cryptorchidism models, suggesting its role in the pathological development of cryptorchidism." (PMID 40486678, 2025). "This study identifies EIF4EBP1, a translation inhibitor modulated by mTORC1, as a pivotal regulator of autophagy in cryptorchidism." (PMID 40486678, 2025). "Here, we hypothesize that E2F1-induced upregulation of EIF4EBP1 exacerbates germ cell autophagy and apoptosis, contributing to cryptorchidism pathogenesis." (PMID 40486678, 2025). "The expression of EIF4EBP1 in cryptorchidism was further investigated using in vitro experiments." (PMID 40486678, 2025). "However, the role of EIF4EBP1 in excessive autophagy in cryptorchidism remained unclear." (PMID 40486678, 2025).
hemangioma (1 paper, 2007). A benign vascular lesion characterized by the formation of capillary-sized or cavernous vascular channels. "In particular, tsc1+/- or tsc2+/- mutant mice which are characterized by high level of mTOR-mediated phosphorylation of Eif4ebp1 and Rps6kb1, have hemangiomas with poorly developed vasculature that are prone to rupture." (PMID 17892597, 2007).
Immunodeficiency (1 paper, 2024). Failure of the immune system to protect the body adequately from infection, due to the absence or insufficiency of some component process or substance. "Therefore, this study proposed that EIF4EBP1 and EPHX1 contribute to immunodeficiency and further affect the prognostic survival status of AML patients by negatively modulating the infiltration level of CD8 T cells and γδT cells." (PMID 39300580, 2024).
intestinal tumor (1 paper, 2018). "These were consistent with qPCR data showing that eif4ebp1 expression, a marker for reduced insulin signaling, was not affected by the intestinal tumor." (PMID 29592890, 2018).
Lipedema (1 paper, 2022). Disorder of adipose tissue characterized by symmetric and bilateral enlargement of the lower extremities due to abnormal deposition of subcutaneous fat often in obese women. "Further studies are needed to understand whether the most different inflammatory markers between these groups (TNFSF14, CASP8, EN-RAGE, EIF4EBP1, ADA, MCP-1) play a mechanistic role in lipedema development and perpetuation." (PMID 36387874, 2022).
myocarditis (1 paper, 2025). Myocarditis is a condition that is characterized by inflammation of the heart muscle (myocardium). "Our findings demonstrate that miR-93-3p directly targets 3′UTR of EIF4EBP1, consistent with prior studies showing that miR-93-3p alleviates renal injury by targeting NFAT5, promotes cellular proliferation and migration via targeting ZFP36L1, and modulates myocarditis by regulating TLR4 expression." (PMID 40900833, 2025).
primary immunodeficiency (1 paper, 2023). "In this study, we have identified four enriched crosstalk genes in primary immunodeficiency, Interferon type I signalling, and translation factors pathways; that is, LCK, PTPRC, EIF4A1, and EIF4EBP1." (PMID 37277696, 2023).
SARS-CoV-infection (1 paper, 2024). "Due to the lack of a role of 4E-BP studies in SARS-CoV-2-related models, the causal link between the increase in the plasma levels of EIF4EBP1 and a severe SARS-CoV-infection is hard to interpret from the functional point of view." (PMID 38455043, 2024).
Tinnitus (1 paper, 2025). Tinnitus is an auditory perception that can be described as the experience of sound, in the ear or in the head, in the absence of external acoustic stimulation. "In addition, eukaryotic translation initiation factor 4E‐binding protein 1 levels (4EBP‐1) (OR = 0.984; 95% CI, 0.97–0.998; p < 0.05) were significantly associated with tinnitus." (PMID 40898658, 2025).
uterine cancer (1 paper, 2021). Primary or metastatic malignant neoplasm involving the uterine corpus and/or the cervix. "In addition, the FOXO3a (forkhead box O3A) /eIF4EBP1 (eIF4E binding protein 1) axis plays a critical role in the inhibitory effect of G129R(a prolactin antagonist) on cell proliferation and cell cycle in uterine cancer." (PMID 34922580, 2021).
tumor (375 papers, 2008 to 2026). "It has been reported that EIF4EBP1 is overexpressed in numerous tumor entities of TCGA and in a pan-cancer analysis of TCGA data, high EIF4EBP1 expression is associated with poor patient outcome." (PMID 38744825, 2024). "In general, phosphorylated EIF4EBP1 is considered as an indicator of oncogenic activity in tumor and associated with poor survival of cancer patients, while unphosphorylated EIF4EBP1 functions as a tumor suppressor." (PMID 25658620, 2015). "We also assessed whether the expression of EIF4EBP1 is determined by NB stages or risk groups, and found that EIF4EBP1 levels are increased according to NB tumor aggressiveness in two cohorts." (PMID 35379801, 2022). "In HER2-positive disease, our findings associate genes such as ARG2, S100A1, MT2A, EIF4EBP1, KLF4, BTG3, and BAG1 to be associated with favourable prognosis through their roles in metabolic regulation, oxidative stress mitigation, and tumour suppression." (PMID 41007296, 2025). "EIF4EBP1 mRNA expression is upregulated in numerous tumor entities and high EIF4EBP1 mRNA levels correlate with poor survival in several cancer types." (PMID 40670359, 2025). "EIF4EBP1 was moderately positive in most normal renal tissues according to CAB005032 staining but strongly positive in most tumor tissues." (PMID 37056387, 2023). "EIF4EBP1 showed a relatively high antibody staining level in tumor tissue when compared to normal tissue, while PALLD presented high protein expression level in normal tissue." (PMID 37885006, 2023). "In conclusion, we found that BP can inhibit AML cell proliferation and tumor growth by downregulating ALKBH5 to repress m6A demethylation of MLST8/EIF4EBP1 mRNA." (PMID 35579750, 2022). "Compared with normal samples, the expression level of CASP7, CDKN1B, EIG4G1, and EIF4EBP1 were significantly increased in the primary tumor samples, while that of CDH3 was significantly decreased." (PMID 35787690, 2022). "Given the prognostic significance of EIF4EBP1/4EBP1 in NB, it is possible that 4EBP1 confers advantages to NB tumor growth or tumor cell survival." (PMID 35379801, 2022). "This indicated that MYCN amplification status, tumor stage and age at diagnosis each influenced the prognostic value of high EIF4EBP1 expression in the SEQC and NRC cohorts." (PMID 35379801, 2022). "To assess the clinical significance of EIF4EBP1 expression, we first examined EIF4EBP1 mRNA levels in NB tumor tissue samples and normal tissues." (PMID 35379801, 2022). "Analysis of their expression levels in tumor patients and normal subjects identified five core prognostic markers, which were EIF4EBP1, BCL2A1, NDRG1, ERRFI1 and BRD4." (PMID 36524001, 2022). "In this study, we analyzed publicly available NB patient data sets and revealed that EIF4EBP1 is overexpressed in NB compared to normal tissues, is significantly co-expressed with MYCN, and is elevated in high-risk relatively to low-risk tumor groups." (PMID 35379801, 2022). "Accordingly, the clinical relevance of EIF4EBP1 expression is strongly dependent on the tumor entity." (PMID 35228525, 2022). "Here, we report that EIF4EBP1 expression levels are significantly elevated in NB compared to corresponding non-tumor tissues and positively correlate with both MYCN expression and MYCN amplification status in at least two independent NB patient cohorts." (PMID 35379801, 2022). "High vs. low tumor grade had relative over-expression of EIF4EBP1 (log2 fold-change = 0.84, 95% CI 0.46, 1.22) and RPS6KB2 (log2 fold-change = 0.33, 95% CI 0.15, 0.50), but under-expression of TSC1 (log2 fold-change = − 0.23, 95% CI − 0.38, − 0.08)." (PMID 35608730, 2022). "In our analysis, EIF4EBP1, IMP3, ATF3, SEC11A and SHC1 also exhibited different expression between BC and non-tumour samples, and were significantly associated with the tumour type, invasive progression, or tumour grade (SupplementaryFigure S2)." (PMID 34187252, 2021).
tumor (continued). "Both PIP4K2A and eIF4EBP1 have been shown to be involved in tumor progression, suggesting a common link between the two." (PMID 34124142, 2021). "For example, the expression of EIF4EBP1 was higher in the tumour tissues (SupplementaryFigure S3A), MIBC (SupplementaryFigure S3B) and high-grade samples (SupplementaryFigure S3C)." (PMID 34187252, 2021). "Unphosphorylated EIF4EBP1 (Cai, Ye & She, 2014), on the other hand, is thought to inhibit tumor activity." (PMID 31938577, 2020). "Eukaryotic initiation factor 4e binding protein (EIF4EBP1), as an important gene regulating autophagy, had been found to be highly expressed in many cancers with poor prognosis of tumor." (PMID 32780567, 2020). "In general, phosphorylated EIF4EBP1 is considered to be an indicator of tumor activity, indicating a worse prognosis." (PMID 31938577, 2020). "The increase in eIF4EBP1 mRNA is somewhat surprising because such an increase would inhibit translation of capped mRNAs that can promote tumour progression." (PMID 26646586, 2016). "The relatively small sample size limits the significance for the relationship of EIF4EBP1 expression with certain important clinical features, such as pathological grade, tumor number and embolus." (PMID 25658620, 2015). "Western blot analysis performed on the expression profiles of the MTOR signal cascade in the tumor adjacent tissues revealed that the treated group expressed a lower level of MTOR/EIF4EBP1/YY1/MYC/SLC2A1 signaling than the untreated group." (PMID 25909713, 2015). "The results indicate that EIF4EBP1 expression, pathology grade, tumor number, encapsulation,embolus and recurrence are significantly associated with OS and DFS." (PMID 25658620, 2015). "EIF4EBP1 is commonly regarded as a tumor suppressor because of its role in repressing translational initiation of mRNAs associated with oncogenic transformation." (PMID 25658620, 2015). "As we uncovered an association between EIF4EBP1 and MYC mRNA expression in MB tissues, and since MYC has been described to control EIF4EBP1 transcription in other tumor types, we asked whether EIF4EBP1 also represents a MYC target gene in MBs." (PMID 40670359, 2025). "Contrary to our findings that high EIF4EBP1 levels significantly correlated with worse patient outcome, a recent report has suggested that 4E-BP1 may act as a tumor suppressor in EwS." (PMID 41100815, 2025). "Moreover, TalaA affected the phosphorylation motif of important transcription factors (e.g., c-Jun) or transcription regulators (e.g., EIF4EBP1), playing a tumor-promoting role via phosphorylation." (PMID 37866481, 2023). "After adjusting tumor purity, the expression of ALOX12B was negatively associated with IGFR1, AKT1, MTOR, and EIF4EBP1, and the same correlation could also be observed in SPRR1A." (PMID 35768785, 2022). "While our data indicate that EIF4EBP1 expression has prognostic power in pediatric cancer, together this supports that EIF4EBP1 expression represents a factor of poor prognosis in a large number of different tumor types." (PMID 35379801, 2022). "However, the prognostic relevance of EIF4EBP1 expression in other individual tumor entities is poorly established, and the mechanisms regulating EIF4EBP1 expression in distinct types of cancer warrant further investigations." (PMID 35228525, 2022). "In keeping with that, the clinical relevance of EIF4EBP1 expression depends on the tumor type." (PMID 35379801, 2022). "EIF4EBP1 gene expression and its clinical relevance in cancer are highly tumor-type specific." (PMID 35228525, 2022). "In previous studies, EIF4EBP1 was involved in tumor occurrence, invasion, and drug resistance." (PMID 35903358, 2022). "The proportion of tumor cells with nuclear phosphorylated eukaryotic translation initiation factor 4E‐binding protein 1 (p4EBP1)‐positive staining was decreased in KURC3 Tem/P1 tumors compared with KURC3 Veh/P1 tumors, but similar between KURC3 Tem/P4 and KURC3 Veh/P4 tumors." (PMID 33107222, 2021).